BMP15 (bone morphogenetic protein 15)
Description:
May be involved in follicular development. Oocyte-specific growth/differentiation factor that stimulates folliculogenesis and granulosa cell (GC) growth.
Synonyms: GDF9B; ODG2; POF4
Tractability: Antibody: UniProt places it where antibodies can reach, with medium confidence; UniProt predicts a signal peptide or a membrane-spanning region; its Gene Ontology location is reachable by antibodies, with medium confidence.
Gene: Protein-coding gene on chromosome X (50,910,735 to 50,916,641, forward strand). Ensembl gene ENSG00000130385.
Subcellular location: Secreted
Pathways (Reactome):
Metabolism of proteins: Post-translational protein phosphorylation; Regulation of Insulin-like Growth Factor (IGF) transport and uptake by Insulin-like Growth Factor Binding Proteins (IGFBPs)
Gene Ontology:
Molecular function: protein binding; cytokine activity; growth factor activity
Biological process: cell surface receptor protein serine/threonine kinase signaling pathway; female gamete generation
Cellular component: endoplasmic reticulum lumen; cytoplasm; extracellular region
Homologues: Orthologues: macaque BMP15 (94% identical), chimpanzee BMP15 (93% identical), rabbit BMP15 (78% identical), dog BMP15 (74% identical), pig BMP15 (74% identical), mouse Bmp15 (63% identical), rat Bmp15 (63% identical), guinea pig BMP15 (57% identical), tropical clawed frog bmp15 (40% identical), zebrafish bmp15 (29% identical). Paralogues in human: GDF9 (30% identical), GDF6 (21% identical), GDF7 (20% identical), GDF5 (19% identical), BMP5 (18% identical), BMP10 (18% identical), GDF2 (18% identical), BMP6 (17% identical), BMP8B (17% identical), BMP7 (17% identical), BMP8A (17% identical), BMP3 (17% identical), and 19 more.
Diseases named in the same sentence as BMP15 in open-access papers:
BMP15 is named in the same sentence as 45 diseases in open-access papers, as found by Europe PMC text mining. Sharing a sentence is not in itself a finding about the gene and the disease. The quoted sentences say what the papers report.
Infertility (32 papers, 2006 to 2025). "A study aiming to identify factors regulating ovulation rate in sheep found that heterozygous carriers of BMP15 mutation had increased ovulation while homozygous were infertile." (PMID 35232444, 2022). "Preliminary studies on knockout models have shown that GDF-9 deficiency led to impaired folliculogenesis and infertility, while a null mutation in the BMP-15 gene caused only reduced fertility in female mice." (PMID 35232444, 2022). "Natural missense and nonsense mutations of ovine BMP15 cause both an increased ovulation rate and infertility, depending on the dosage of the mutant allele." (PMID 33413103, 2021). "As previously reported, natural mutations in BMP15 of sheep can lead to increased ovulation rate and litter size in heterozygotes but infertility in homozygotes due to bilateral ovarian hypoplasia." (PMID 31803742, 2019). "BMP15 gene variations linked to various ovarian phenotypic consequences subject to the species, from infertility to improved prolificacy in sheep, primary ovarian insufficiency in women or associated with minor subfertility in mouse." (PMID 29177034, 2017). "In contrast to Bmp15 null mice, in sheep, the naturally-occurring homozygous mutants (FecXI) that has point mutations in the coding region of BMP15 gene causes the infertile due to an arrest at the primary stage of folliculogenesis." (PMID 26516845, 2015). "In mice, BMP15 mutations may lead to decreased reproductive capacity or infertility, while, in sheep, homozygotes inhibit follicular development, resulting in infertility." (PMID 40867768, 2025). "Thus, the BMP15 mutation increases the litter size, probably as a result of an increased ovulation rate, and causes infertility in a dosage-sensitive manner (one T-allele increases the litter size, two T-alleles cause infertility)." (PMID 33413103, 2021). "As an example of this hypothesis, it is known that mutations of the bone morphogenetic protein 15 (BMP-15) gene cause infertility in sheep and POF in humans while mice show normal follicle development." (PMID 31690065, 2019). "In conclusion, our study suggests that the reduction of GDF9 and BMP15 expression starting from the primary follicle stage can cause follicular development disorders and insufficient oocyte maturation that can further lead to subfertility or infertility." (PMID 28903889, 2018). "Although effects of FecGH and FecGT variants have never been tested in vitro, it is strongly thought that GDF9 loss-of-function mutations might alter both GDF9 homodimer and BMP15/GDF9 heterodimer pathways leading to infertile animals." (PMID 23637641, 2013). "On the other hand, if an animal’s status is assessed based on the objective criterion of fertility (i.e., an animal having one or more litters), the hypothesis that the nonsense mutation of BMP15 causes underdeveloped external sexual organs and consequent infertility remains valid." (PMID 33413103, 2021). "Indeed, whereas mutations in the BMP15 gene cause infertility in ewes due to defects in folliculogenesis and have been associated with premature ovarian failure (POF) in women, most defects in female mice lacking the bone morphogenetic protein BMP15 are confined to the ovulation process." (PMID 21851638, 2011). "Sources revealed 235 different genes linked to ovulatory dysfunction and infertility including follicle-stimulating hormone receptor (FSHR), luteinizing hormone/choriogonadotropin receptor (LHCGR), and bone morphogenic protein 15 (BMP15)." (PMID 40535332, 2025). "The present findings suggest that the serum BMP15 and kisspeptin concentrations can be used to predict the success of infertility treatment in obese patients." (PMID 37790202, 2023). "Defects in Bmp15 have been related to ovarian pathologies and infertility, including altered ovulation, PCOS, and POI." (PMID 35972313, 2022).
Infertility (continued). "Both studies have provided essential information on the expression of GDF-9 and BMP-15 in infertile couples undergoing IVF and the promising clinical use of the OSF as non-invasive markers to predict oocyte competence." (PMID 34527670, 2021). "In humans, BMP15 mutations have been associated with primary ovarian insufficiency (POI) and infertility phenotype in women." (PMID 31803742, 2019). "Bone morphogenetic protein 15 (BMP15) is an X-linked gene, which is exclusively expressed in ovaries, in the oocytes of late primary follicles, and it is associated with infertility and ovarian dysgenesis (OD), even in heterozygotes." (PMID 26173456, 2015). "Notable exceptions are missense mutations of BMP15 in the Grivette and Olkuska sheep breeds, as they do not cause infertility." (PMID 33413103, 2021). "However, knockdown of BMP15 in the poly-ovulatory species swine completely inhibits ovarian follicular development, leading to infertility." (PMID 33413103, 2021). "The BMP15 fecundity alleles show an X-linked overdominance inheritance pattern with infertility in homozygous females, while the GDF9 fecundity alleles have an autosomal overdominance inheritance pattern with infertility in homozygous females." (PMID 17205129, 2006). "Ovarian failure in humans has been associated with immunity-related disorders and genetic factors, such as genetic variants in BMP15, but the specific immune cells and mechanisms that drive premature follicle loss, infertility, and masculinization were not known." (PMID 37992158, 2023). "Thus, BMP15 is related to infertility and super-fertility in a dosage-sensitive manner in sheep." (PMID 26516845, 2015). "In cattle, GDF9 and BMP15 play indispensable roles in follicular development and the ovulatory process, while in humans, mutations or deficiencies in these factors are more often associated with diminished ovarian reserve or subfertility rather than absolute infertility." (PMID 41462676, 2025). "BMPR2 activation influences granulosa cell proliferation, BMP15 and GDF9 signaling, and disruptions in this pathway can lead to infertility and reproductive abnormalities." (PMID 38275408, 2024). "Blood genomic DNA was extracted from a subset of low-ovulating, prolific and infertile ewes of the “W” flock, and the entire coding sequences of GDF9 and BMP15 were sequenced." (PMID 28506298, 2017). "BMP15 genetic alterations have been noted in cases of POI and infertility in humans." (PMID 39976580, 2025). "Landmark studies have demonstrated that homozygous loss of function mutations of GDF9 in mice and sheep and of BMP15 in sheep results in infertility, with follicles arrested at the primary stage, although mice lacking BMP15 expression remain fertile." (PMID 37171807, 2023). "An increased understanding of BMP15/GDF9 signaling during human oocyte maturation may improve the clinical treatment for women with ovulation dysfunction and infertility, especially in connection with in vitro maturation (IVM)." (PMID 35986324, 2022). "In GDF9-null mice, folliculogenesis does not progress beyond the primary stage, while BMP15-null mice have impaired oocyte maturation that leads to infertility." (PMID 29047400, 2017). "In the GDF9 null mice folliculogenesis does not progress beyond the primary stage, while BMP15 null mice had impaired oocyte maturation leading to infertility." (PMID 25543533, 2014). "No streak ovaries, which are considered indicators of infertility due to homozygocity forsome mutations in GDF9 and BMP15, were found." (PMID 25210607, 2012). "When mice are experimentally rendered infertile by cyclophosphamide, treatment with conditioned medium and PRP was able to boost expression of ‘mothers against decapentaplegic’ homologs 1 and 2 (SMAD1, SMAD2), growth differentiation factor-9 (GDF9), and bone morphogenetic protein-15 (BMP15)." (PMID 37505061, 2023).
Infertility (continued). "Similarly, a study that involved 196 infertile couples undergoing IVF, revealed that the COCs of women who achieved pregnancy expressed higher GDF-9 and BMP-15 mRNA concentrations than those who did not achieve pregnancy." (PMID 34527670, 2021).
premature ovarian failure (13 papers, 2011 to 2025). "The occurrence of FSHR, INHA, ESR1, and BMP15 gene polymorphisms has also been reported to be associated with various reproductive diseases, including primary ovarian insufficiency (POI), pregnancy loss, and preeclampsia." (PMID 37239044, 2023). "We examined SNPs in FSHR, INHA, ESR1, and BMP15, which have been associated with primary ovarian failure." (PMID 37239044, 2023). "The large number of mutations in the GDF9 and BMP15 genes have been identified in women with premature ovarian failure and in mothers of dizygotic twin." (PMID 36139716, 2022). "In women, mutations in BMP15 have been found associated with both primary and secondary amenorrhea in several primary ovarian insufficiency (POI) cohorts with prevalence between 1.5% and 15%." (PMID 24147118, 2013). "GDF9 and BMP15 are associated with premature ovarian failure." (PMID 37108426, 2023). "In human genetic studies, GDF9 and BMP15 variants are found in women with premature ovarian failure and amenorrhea, suggesting that GDF9 and BMP15 could be potential PCSK6 substrates in the ovary." (PMID 36362216, 2022). "Alterations of the BMP15 gene have been found associated with different ovarian phenotypic effects depending on the species, from sterility to increased prolificacy in sheep, slight subfertility in mouse or associated with primary ovarian insufficiency (POI) in women." (PMID 24147118, 2013). "We identified CBX2 regulated genes associated with polycystic ovary syndrome (PCOS) such as TGFβ, MAP3K15 and DKK1, as well as genes implicated in premature ovarian failure (POF) (i.e. POF1B, BMP15 and HOXA13) and the pituitary deficiency (i.e. LHX4 and KISS1)." (PMID 31745224, 2019). "In recent years, several studies have investigated the pathological processes of primary ovarian insufficiency (POI) concerning two members of the TGF-β superfamily, BMP15 and GDF9." (PMID 40969411, 2025). "Notably, FMR1, DIAPH2, POD1B, and BMP15 were previously designated as premature ovarian failure (POF) loci, namely, POF1, POF2A, POF2B, and POF4, respectively." (PMID 37033245, 2023).
sterility (10 papers, 2013 to 2025). "In sheep, it has been shown that homozygous mutants of GDF9 and BMP15 cause ovarian failure, which leads to sterility." (PMID 37239462, 2023). "Naturally occurring mutations in growth and differentiation factor 9 (GDF9) or bone morphogenetic protein 15 (BMP15) genes are associated with increased ovulation rate (OR) and litter size (LS) but also sterility." (PMID 28506298, 2017). "In contrast, in sheep different BMP15 mutations were associated with sterility." (PMID 39850788, 2025). "Importantly, BMP15 has been shown to be essential for female fertility in most mammalian species; in particular, homozygosity for BMP15 mutations leads to subfertility in mice and sterility in sheep." (PMID 31683967, 2019). "Similarly to sheep, a large number of mutations in the GDF9 and BMP15 genes have been described in women with fertility disorders." (PMID 23637641, 2013). "In a previous study in sheep, the rate of ovulation in BMP15 mutants was greater in heterozygotes, whereas the homozygous mutants showed a primary ovarian failure, which led to sterility." (PMID 37239462, 2023). "BMP15 (also known as GDF9B), is co-expressed with GDF9 in oocytes and also shows species differences in its function: loss of BMP15 in sheep leads to sterility while in mice its loss has a mild effect on fertility." (PMID 25790371, 2015). "Particularly, two landmark studies demonstrated that the absence of two oocyte-specific growth factors, GDF9 and BMP15, causes sterility (mouse:; sheep:)." (PMID 32316494, 2020). "Indeed, the effect on ovulation rate and sterility can be reproduced in sheep and cattle through adapted immunization regimens, neutralizing more or less BMP15 or GDF9, and confirms the crucial role of these two factors." (PMID 32316494, 2020). "Our findings suggest an additional role of the BMP15 protein in folliculogenesis and could contribute to a better understanding of the pathogenesis of women′s fertility disorders." (PMID 23637641, 2013). "Our results bring new insights into the key role played by the BMP15 protein in ovarian function and could contribute to a better understanding of the pathogenesis of women′s fertility disorders." (PMID 23637641, 2013).
ovarian failure (9 papers, 2009 to 2024). "This forms a signaling axis in germ cells, triggered by the loss of Bmp15, which activates macrophages, leading to ovarian failure and masculinization." (PMID 39763589, 2024). "In humans, ovarian insufficiency can be caused by autoimmune and genetic factors, including mutations in BMP15." (PMID 39763589, 2024). "In heterozygotes, there are high ovulation rates in GDF9 and BMP15 mutants while the homozygous mutants show a primary ovarian failure, causing complete sterility." (PMID 37239462, 2023). "Even though earlier investigations regarding mutational analysis of BMP-15 gene were associated with ovarian failure, reports on BMP-15 gene in PCOS are also available." (PMID 27679828, 2016). "An increasing number of studies have documentedautosomal involvement in ovarian dysfunction.Heterozygous mutation of the bone morphogeneticprotein 15 (BMP15) gene has been reported in twosisters with POF." (PMID 24963360, 2011). "For instance, we have recently detected a BMP15 mutation leading the potentially damaging variant S5R in a patient with severe ovarian dysfunction." (PMID 19607682, 2009). "In these sheep, ewes with single allele of inactive BMP15 gene showed increased ovulation rate and a higher incidence of twin or triplet births, whereas ewes with bi-alleles of inactive BMP15 gene were sterile with primary ovarian failure phenotype." (PMID 31803742, 2019). "We found that csf1ra mutants heterozygous for csf1rb, which eliminates primitive and most definitive macrophages, prevented ovarian failure and sex reversal of bmp15 mutants." (PMID 37992158, 2023). "bmp15 mutants initially develop as females but undergo ovarian failure and sex reversal, presumably due to granulosa cell and estrogen deficiencies." (PMID 37992158, 2023). "S2G), allowed us to assess the contribution of each macrophage population and to effectively deplete or remove macrophages at the onset of ovarian failure in bmp15 mutants." (PMID 37992158, 2023). "We found that removing Csf1a was sufficient for sustained suppression of ovarian failure and sex reversal of bmp15 mutants, indicating that Csf1a drives ovary-to-testis transformation." (PMID 37992158, 2023). "We observe signals of positive selection on the BMP15 gene, related to ovarian insufficiency in women and subjected to positive selection in Hominidae clade." (PMID 34646300, 2021). "The cellular mechanisms underlying ovarian failure caused by BMP15 mutation and immune contributions are not understood." (PMID 37992158, 2023). "Consistent with a role for Il34 in promoting oocyte loss, removal of Il34 suppressed ovarian failure of bmp15 mutants, but, unlike loss of Csf1a, eliminating Il34 only delayed the ovary-to-testis transition." (PMID 37992158, 2023). "Therefore, Bmp15 has a conserved function in signaling from the oocyte to promote growth, survival, and progression of ovarian follicles, which prevents ovarian failure in zebrafish." (PMID 37992158, 2023). "To determine whether ovarian failure and sex reversal requires a threshold number or a unique subtype of macrophages, we analyzed compound mutants for various combinations of csf1ra/b and found that bmp15 mutants lacking only csf1ra were all male as adults." (PMID 37992158, 2023).
polycystic ovary syndrome (9 papers, 2016 to 2025). A disorder that manifests as multiple cysts on the ovaries. "Previously, FSRH, INHA, ESR1, and BMP15 gene polymorphisms have been studied with regard to the conditions of the female reproductive system, including polycystic ovary syndrome, poor ovarian response, POI, breast cancer, and endometriosis, as well as male infertility." (PMID 37239044, 2023). "BMP-15 mutations may be important in cessation of follicle development and hence results in accumulation of small antral follicles and development of polycystic ovary phenotype." (PMID 27679828, 2016). "Alterations of BMP15 and GDF9 were also searched in association with polycystic ovary syndrome (PCOS)." (PMID 32636872, 2020). "Studies showed that BMP15 was involved in polycystic ovary syndrome (PCOS)." (PMID 29409506, 2018). "Some studies show no significant androgen effect on AMH, while others suggest a potential influence in conditions like polycystic ovary syndrome (PCOS) BMPs stimulate AMH and AMHR2 expression, with BMP15, often with GDF9, enhancing AMH expression." (PMID 40410629, 2025).
female infertility (6 papers, 2015 to 2023). Diminished or absent ability of a female to achieve conception. "The loss of BMP15 in sheep leads to female infertility with underdeveloped ovaries containing primary follicles only; however, its loss in mice does not generate significant impact on ovarian development and reproductive performance." (PMID 37713421, 2023). "Whereas Bmp15 null females are subfertile, the additional deletion of a single Gdf9 allele (i.e., Bmp15-/-/Gdf9+/-; hereafter double-mutant, DM) results in female infertility at least in part due to the defective development of cumulus cells." (PMID 36424497, 2022). "As it may be observed, BMP-15 seems to be an important factor in female infertility affecting embryonic arrest, as it has been observed that its embryonic differential expression may hinder the developmental potential." (PMID 34361119, 2021).